NR4A1 (nuclear receptor subfamily 4 group A member 1)
Diseases named in the same sentence as NR4A1 in open-access papers (continued):
Sharing a sentence is not in itself a finding about the gene and the disease.
tumor (continued). "NR4A1/NR4A3 silencing in AML is mediated through the blockade of transcription elongation, while treatment with dihydroergotamine (DHE) rescued NR4A silencing and allowed their tumor-suppressing ability to reactivate with concomitant slowing of AML progression in vivo." (PMID 33634114, 2021). "Kaempferol and quercetin also inhibited tumor growth in an athymic nude mouse model in vivo suggesting that these nutraceuticals can be repurposed and used in a precision medicine/nutrition approach for treating RMS patients and possibly patients with other cancers that express NR4A1." (PMID 34906197, 2021). "On the other hand, we also could not exclude another possibility that NR4A1 protein might be induced in 231-Ctrl tumor cells in the tumor environment." (PMID 28903348, 2017). "Surprisingly, NR4A1 protein was detected at similar levels in both 231-Ctrl and 231-NR4A1 tumors, suggesting that the much higher level of NR4A1 protein in 231-NR4A1 cells versus 231-Ctrl cells failed to maintain during the growth and progression period in the 231-NR4A1 tumor cells." (PMID 28903348, 2017). "Indeed, we found that expression of NR4A1 in MDA-MB-231 cells inhibited JNK1 expression, c-Jun activation and cyclin D1 expression, which is correlated with the decreased cell proliferation and tumor growth of these cells." (PMID 28903348, 2017). "In addition, DIM-C-pPhOH (30 mg/kg/d) also decreased expression of TXNDC5 and IDH-1 and induced CHOP expression in tumors from athymic nude mouse xenografts, demonstrating that C-DIM/NR4A1 antagonists-dependent inhibition of RCC cell and tumor growth is due, in part, to induction of stress." (PMID 26035713, 2015). "NR4A1 expression reduces migration in both normal and tumour lines, as well as altering adhesion to the extracellular matrix (ECM) and integrin cell surface expression in MCF-10A cells, suggesting that NR4A1 may have an inhibitory role in relation to invasion/metastasis development." (PMID 20642837, 2010). "In addition, lack of NR4A1 results in reduced levels of colony-stimulating factor-1 receptor (CSF-1R) expression, which decreases the migratory capacity of inflammatory cells and subsequently hinders cell chemotaxis and tumor infiltration." (PMID 33634114, 2021). "In contrast, the TF motifs (e.g., NR4A1, NR4A2, and NR4A3) orchestrating T-cell exhaustion were exclusively enriched in tumor-specific Tex cells but not in plaque-specific Tem cells." (PMID 38491170, 2024). "Mice lacking NR4A1 and NR4A2 genes, specifically in Treg cells, show resistance to tumor growth in transplantation models without exhibiting any serious systemic autoimmunity." (PMID 33634114, 2021). "Next, to specifically investigate whether I-NCMs can induce tumor lysis independent of T cells, we pharmacologically depleted CD4+ and CD8+ T cells in Nr4a1–/– mice and evaluated the efficacy of I-NCMs." (PMID 39545417, 2024). "Tumor promotion resulting from NR4A1 knockout was abolished when ID1 was knocked out simultaneously, whereas the tumor inhibitory effect of ID1 knockout was not significantly affected by NR4A1 knockout." (PMID 33990575, 2021).
cancer (801 papers, 1995 to 2026). A tumor composed of atypical neoplastic, often pleomorphic cells that invade other tissues. "Among them, CUX1, IKZF3, and NR4A1 (highlighted in red in the figure) are well-documented cancer-associated factors." (PMID 40923764, 2025). "Recently, it was shown that components of the AP-1 transcription factor (FOS, FOSB, JUN), EGR1, and NR4A1 behave as a conserved co-regulated group of genes whose expression is associated with ZFP36 in cancer cells." (PMID 39026155, 2024). "NR4A1 is a transcription factor that is dysregulated in different cancer types, involved in T-cell dysfunction, and associated with the development of fibrotic diseases." (PMID 38791553, 2024). "NR4A1, also known as Nur77, is a transcription factor that has been implicated in the development and progression of various types of cancer, including COAD." (PMID 37564873, 2023). "NR4A1 is highly expressed in various human tumors and is known to regulate pathways and genes associated with cancer cell proliferation, survival, migration, and invasion." (PMID 35563670, 2022). "Functional studies on solid tumor-derived cancer cells have demonstrated that NR4A1 regulates genes and pathways associated with cell proliferation, survival, migration/invasion, and TGFβ-induced invasion (rev." (PMID 34072371, 2021). "NR4A1 has been characterized as a pro-oncogenic factor in many solid tumors and regulates cancer cell growth, survival, migration, invasion, and associated genes." (PMID 34906197, 2021). "Among them, six transcription factors regulating the cancer stem cell-associated genes were verified by the reported literatures (marked with deep red), including NR4A1, FOS, KLF-4, GLI1, NFATC1 and JUN." (PMID 32242101, 2020). "OBJECTIVE: Fenretinide is reported to induce NR4A1-associated apoptosis in several types of cancer cells." (PMID 31839811, 2019). "NR4A1 is also implicated in regulating the proliferation, apoptosis and cell cycle arrest of cancer cells." (PMID 31839811, 2019). "We observed a significant association between high cytoplasmic NR4A1 and favourable cancer-specific survival and the germinal centre B cell-like subtype, respectively." (PMID 30266952, 2018). "NR4A1 is a nuclear receptor; however, treatment of some cancer cell lines with apoptosis-inducing agents results in the induction and nuclear export of NR4A1 which associates with mitochondrial bcl-2 to form a pro-apoptotic complex." (PMID 26035713, 2015). "A second NR4A1-regulated pathway in cancer cells is associated with regulation of genes such as TXNDC5 and IDH1 that maintain high levels of redox equivalents and decrease intracellular stress." (PMID 26035713, 2015). "Nr4a1 is involved in a wide range of functions related to maintaining homeostasis, and thus, its dysregulation has been implicated in a number of pathological conditions including cancer, metabolic disease, inflammation, and cardiovascular disease." (PMID 39644367, 2024). "Decreased Nr4a1 showed a significant association with poor cancer-specific survival, suggesting that Nr4a1 could be used as an independent prognostic indicator." (PMID 31683815, 2019). "However, the development of NR4A1-targeted therapies will be dependent on further research to better understand lineage-specific roles of NR4A1 and the underlying mechanisms across different cancer types and immune cells." (PMID 40508074, 2025). "In contrast, results of RNAi studies suggest that nuclear NR4A1 is pro-oncogenic and plays a role in cancer cell proliferation and survival, and studies in this laboratory have identified at least three pathways and associated genes that contribute to the functions of NR4A1 in cancer cells." (PMID 26035713, 2015). "NR4A1-responsive Rh30 cancer cells were used as models to determine NR4A1-dependent transactivation, cell growth inhibition and inhibition of specific gene products, and in some studies, knockdown of NR4A1 by RNA interference was also determined." (PMID 41901052, 2026).
cancer (continued). "Recent studies show that quercetin, tetrandrine and flavonoids bind NR4A1 and inhibit NR4A1-dependent pro-oncogenic pathways and genes in breast and other cancer cell lines." (PMID 40313760, 2025). "By using these molecular tools, the therapeutic potential of NR4A1 targeting in cancer therapy and the resultant immunological responses have been explored." (PMID 40508074, 2025). "To determine the role of NR4A1 in cancer metabolism, we performed a comprehensive untargeted mass spectrometric metabolomics analysis in NR4A1-knockout and parental control BC cells." (PMID 40164686, 2025). "Specifically, NR4A1 is an active player in metabolic processes related to cancer progression, including mediating processes such as glycolysis, fatty acid synthesis, and amino acid metabolism." (PMID 40508074, 2025). "Interactions of NR4A2 and NR4A3 with Sp1/Sp4 to activate or deactivate gene expression have not been characterized; however, there is considerable evidence that NR4A1 interacts with Sp1 and Sp4 to regulate several genes in cancer cell lines." (PMID 39858066, 2025). "NR4A1 expression is induced by various stress factors, and NR4A1is involved in the regulation of cell growth, apoptosis, the immune system, and various cancers." (PMID 40746844, 2025). "This specificity opens avenues for using hydroxyflavones as nutraceutical interventions targeting NR4A1, with the potential to improve the efficacy of existing cancer treatments." (PMID 39803270, 2025). "For example, NR4A1 levels increase in many solid tumor-derived cancer cells with enhanced metabolic rates." (PMID 40137111, 2025). "NR4A1 plays a pro-apoptotic role in a variety of cancers, in part because of its localization in the nucleus." (PMID 40666103, 2025). "Further research is necessary to determine the specific mechanism behind NR4A1′s impact on the NF-κB pathway in DCs and the role of NR4A1 in DCs within a cancer-specific context." (PMID 40508074, 2025). "NR4A1 plays a multi-effect regulatory role and although it is generally accepted that NR4A1 has a pro-cancer effect, the correlation between high expression and adverse clinical outcomes is controversial." (PMID 40666103, 2025). "The therapeutic efficacy of these compounds is enhanced by their capacity to act as NR4A1 antagonists, making them promising candidates for precision oncology, particularly in cancers overexpressing NR4A1." (PMID 39803270, 2025). "A few studies have found a role for NR4A1 in macrophages related to both their physiological and pathological functions in cancer." (PMID 40508074, 2025). "Among the many structurally diverse compounds that bind NR4A1, the natural product cytosporone B (CsnB) has been the most widely used for determining effects on NR4A1-regulated non-cancer endpoints." (PMID 40871737, 2025). "Results of NR4A1 knockdown studies show that this receptor is pro-oncogenic in solid tumors and regulates cancer cell proliferation, survival, migration and invasion and plays a role in T-cell exhaustion." (PMID 40332813, 2025). "NR4A1 (Nur77): Studies on the identification function of NR4A1-regulated genes in cancer cells have been investigated in NR4A1 knockdown studies, and it was observed that several DEGs contained GC-rich promoter, and many did not contain cognate NBREs or NuREs." (PMID 39858066, 2025). "Flavonoids exhibit significant modulatory effects on orphan nuclear receptor 4A1 (NR4A1), an important factor in cancer biology." (PMID 39803270, 2025). "A limited number of studies have indicated a role for NR4A1 in regulating B cell activity in relation to cancer." (PMID 40508074, 2025). "In the present study, our results indicated the overlooked impact of NR4A1 on cancer cell metabolism." (PMID 40164686, 2025). "NR4A1 is differentially expressed in multiple cancer types and has cancer type-specific biological functions that are dependent on its transcriptional targets." (PMID 40164686, 2025).
cancer (continued). "NR4A1 is a regulator of lipid metabolism in non-cancer tissues such as the liver and can reduce SREBP1 expression and activity in cancer cells." (PMID 40427160, 2025). "NR4A1 target genes include those involved in metabolic reprogramming, making it a prospective therapeutic target for altering metabolic pathways in cancer." (PMID 40508074, 2025). "Analysis of TCGA data revealed that the chromatin accessibility of the NR4A1-downstream RE is positively correlated with NR4A1 expression in specific cancer types, as we observed in HeLa cells." (PMID 38791553, 2024). "Here, we report a first-of-its-kind NR4A1-targeting PROTAC named NR-V04 as a lead for cancer therapy." (PMID 38334978, 2024). "In the first study, the lead candidate (E)-5-[(8-methoxy-2-methylquinolin-4-yl)amino]-N’-(4-methylthio)benzylidene-1H-indole- carbohydrazide bound NR4A1 with a KD of 3.58 μM and was highly cytotoxic to cancer cell lines." (PMID 38116863, 2024). "Increasing evidence suggests that NR4A1 has several metabolic functions in cancers and is involved in regulating glycolysis, fatty acid synthesis, and the metabolism of glutamine and amino acids." (PMID 38539632, 2024). "CsnB also inhibited cancer cell growth, and induced apoptosis and the latter response was also due, in part, to nuclear export of NR4A1." (PMID 38116863, 2024). "Subsequent studies showed that 4-hydroxyphenyl (DIM8) and 4- carbomethoxy-phenyl (DIM14) analogs activated NR4A1-dependent transactivation in cancer cells and also bound NR4A1 in a direct binding assay that measured fluorescent quenching of a Trp in the LBD." (PMID 38116863, 2024). "Then, we experimentally evaluated the effect of the NR4A1/MALAT1 axis on specific cancer types through MALAT1 downregulation and CRISPR-i assays." (PMID 38791553, 2024). "Here, we establish NR4A1 as a valid target for cancer immunotherapy and describe a first-of-its-kind proteolysis-targeting chimera (PROTAC, named NR-V04) against NR4A1." (PMID 38334978, 2024). "Our findings delineate the molecular mechanism of MALAT1 that fine-tunes the expression of specific cancer modulators, such as NR4A1, by regulating the chromatin accessibility of an NR4A1-downstream RE." (PMID 38791553, 2024). "These cancer-specific effects led us to evaluate the correlation between accessibility for both peaks and NR4A1 expression in different cancer types." (PMID 38791553, 2024). "Following MDP treatment, we found RFP+ cells around cancer colonies in Nr4a1–/– Nod2–/– mice that received either Ccr2RFP/RFP or Ccr2RFP/+ bone marrow." (PMID 39545417, 2024). "The intensity of both ATAC-seq peaks was positively correlated with NR4A1 expression in all cancer types." (PMID 38791553, 2024). "In summary, this study describes a series of structurally related bis-indole compounds that bind both NR4A1 and NR4A2 and are dual receptor ligands that act as inverse NR4A1/2 agonists in cancer cell lines." (PMID 38540704, 2024). "Studies have shown that NR4A1 plays a crucial role in the development and progression of various diseases, such as cancer, cardiovascular disease, metabolic disorders, and neurodegenerative diseases." (PMID 37564873, 2023). "Recent studies show that polyphenolic compounds such as quercetin, kaempferol, broussochalcone and resveratrol bind the orphan nuclear receptor NR4A1, and in cancer cell models these compounds act as NR4A1 antagonists." (PMID 37175855, 2023). "In cancer cells, translocation of NR4A1 from the nucleus to the mitochondrion has been shown to lead to apoptosis." (PMID 39872303, 2023). "NR4A1 regulates cancer cell proliferation, survival, cell cycle progression, migration, and invasion in multiple solid tumor-derived cell lines." (PMID 37847301, 2023). "Cancer therapeutics response analysis revealed that the expression level of NR4A1 can influence the response to specific drugs." (PMID 37564873, 2023).
cancer (continued). "In cancer cells inverse NR4A1 agonists decrease cancer cell growth, induce apoptosis and inhibit migration/invasion and treatment of RKO, SW480 and HCT116 cells with 7.5 and 15 μM piperlongumine inhibited cell growth as determined in an XTT assay." (PMID 37808182, 2023). "It was recently reported that the hydroxyflavones quercetin and kaempferol bind the orphan nuclear receptor 4A1 (NR4A1, Nur77) and act as antagonists in cancer cells and tumors, and they inhibit pro-oncogenic NR4A1-regulated genes and pathways." (PMID 37175855, 2023). "Ongoing research in our laboratories has been focused on the role of nuclear receptor 4A1 (NR4A1) in cancer and inflammatory diseases." (PMID 37847301, 2023). "To analyze the correlation between NR4A1 expression and chemical compound sensitivities, we used the Cancer Therapeutics Response Portal (CTRP) v2 database." (PMID 37564873, 2023). "From the literature, increasing evidence proves that among these NR4A receptors, NR4A1 shows more metabolic functions in cancers, such as regulating glycolysis and exhibiting activities in fatty acid synthesis, glutamine, and amino acid metabolism." (PMID 36052242, 2022). "This evidence is proved that the effect of NR4A1 in regulating lipid metabolism in cancer growth and proliferation." (PMID 36052242, 2022). "Compared to clinically applicable GWs, (Z)-BP in CW can not only reduce nuclear receptor subfamily 4 group A member 1 (Nur77) to increase cancer cell apoptosis, but also inhibit telomerase reverse transcriptase (TERT) to promote cell senescence." (PMID 35646111, 2022). "The expression and functions of NR4A1 in cancer metabolism are emerging as a promising area in treating and preventing human cancer malignant evolvement." (PMID 36052242, 2022). "This study shows for the first time that TTD, which exhibited the highest inhibition of NR4A1-dependent activity among FCN analogs, directly binds to the LBD of NR4A1 and antagonizes NR4A1-mediated transactivation in cancer cells." (PMID 35563670, 2022). "NR4A1 is an orphan nuclear receptor that exhibits pro-oncogene or anti-cancer effects in different cancers." (PMID 36052242, 2022). "Previous studies have shown in HCC it has been demonstrated that NR4A1 suppresses glycolysis in different cancers." (PMID 35547878, 2022). "Through a literature review, we found that NR4A1 was reported as a key factor for cancer initiation and progression, therefore was selected for the further study." (PMID 36566195, 2022). "Basic on this, this review highlighted the diverse metabolic roles of NR4A1 in cancers, which provides vital references for the clinical application." (PMID 36052242, 2022). "In a recent study, this laboratory identified fangchinoline (FCN), a plant-derived NR4A1 inactivator, and showed its NR4A1-dependent anticancer activities in various cancer cell lines." (PMID 35563670, 2022). "Previous studies have shown that NR4A1 silencing and that the NR4A1 antagonist reduced cell proliferation and induced apoptosis in many different cancer cell lines, including Panc-1 cells." (PMID 35563670, 2022). "The results in the present study enhance our understanding of the antitumor mechanisms of TTD and suggest that TTD can be used alone or in drug combinations for targeted therapy for cancer patients overexpressing NR4A1." (PMID 35563670, 2022). "Together, these studies demonstrate that NR4A1 is a prospective therapeutic target with translational potential for several human cancers by targeting the vasculature within the TME." (PMID 33634114, 2021). "Located in the nucleus, NR4A1 also plays a vital role in cell survival and apoptosis in a variety of cancer cells and tumors." (PMID 33923503, 2021). "The effects of class IIa HDACs on Er+ cancer cells proliferation can also be explained by the repression of NR4A1/Nur77 operated by these enzymes." (PMID 33671588, 2021).